SNAI1 (snail family transcriptional repressor 1)
Description:
Involved in induction of the epithelial to mesenchymal transition (EMT), formation and maintenance of embryonic mesoderm, growth arrest, survival and cell migration. Binds to 3 E-boxes of the E-cadherin/CDH1 gene promoter and to the promoters of CLDN7 and KRT8 and, in association with histone demethylase KDM1A which it recruits to the promoters, causes a decrease in dimethylated H3K4 levels and represses transcription. The N-terminal SNAG domain competes with histone H3 for the same binding site on the histone demethylase complex formed by KDM1A and RCOR1, and thereby inhibits demethylation of histone H3 at 'Lys-4' (in vitro). During EMT, involved with LOXL2 in negatively regulating pericentromeric heterochromatin transcription. SNAI1 recruits LOXL2 to pericentromeric regions to oxidize histone H3 and repress transcription which leads to release of heterochromatin component CBX5/HP1A, enabling chromatin reorganization and acquisition of mesenchymal traits (By similarity). Associates with EGR1 and SP1 to mediate tetradecanoyl phorbol acetate (TPA)-induced up-regulation of CDKN2B, possibly by binding to the CDKN2B promoter region 5'-TCACA-3. In addition, may also activate the CDKN2B promoter by itself.
Synonyms: SNAH; SNA; SLUGH2; SNAIL1; SNAIL; dJ710H13.1
Tractability: Small molecule: a structure with a bound ligand is known. PROTAC: UniProt records ubiquitination sites on it; ubiquitination databases record sites on it.
Gene: Protein-coding gene on chromosome 20 (49,982,980 to 49,988,886, forward strand). Ensembl gene ENSG00000124216.
Subcellular location: Nucleus; Cytoplasm
Subcellular location (Human Protein Atlas): Nucleoplasm
Pathways (Reactome):
Cell-Cell communication: Negative Regulation of CDH1 Gene Transcription; Regulation of CDH11 gene transcription
Developmental Biology: Epithelial-Mesenchymal Transition (EMT) during gastrulation
Signal Transduction: Regulation of PTEN gene transcription
Gene Ontology:
Molecular function: DNA-binding transcription repressor activity, RNA polymerase II-specific; E-box binding; kinase binding; protein binding; RNA polymerase II transcription regulatory region sequence-specific DNA binding; sequence-specific double-stranded DNA binding; RNA polymerase II cis-regulatory region sequence-specific DNA binding; sequence-specific DNA binding
Biological process: canonical Wnt signaling pathway; epithelial to mesenchymal transition; negative regulation of intrinsic apoptotic signaling pathway in response to DNA damage; negative regulation of transcription by RNA polymerase II; negative regulation of vitamin D biosynthetic process; osteoblast differentiation; positive regulation of cell migration; positive regulation of DNA-templated transcription; positive regulation of epithelial to mesenchymal transition; regulation of bicellular tight junction assembly; aortic valve morphogenesis; epithelial to mesenchymal transition involved in endocardial cushion formation; heterochromatin organization; mesoderm formation; Notch signaling pathway; regulation of DNA-templated transcription; mesenchymal cell differentiation; negative regulation of DNA-templated transcription
Cellular component: cytoplasm; nucleoplasm; nucleus; pericentric heterochromatin
Genetic constraint (gnomAD): Loss-of-function variants: 15 observed, 25.78 expected, observed/expected ratio (o/e) 0.58, 90% interval 0.39 to 0.9. The upper end of that interval is the gene's LOEUF score, 0.9, which puts it in group 3 of 6, group 1 being the genes least tolerant of losing a copy. Missense variants: 283 observed, 349.94 expected, observed/expected ratio (o/e) 0.81, 90% interval 0.73 to 0.89. Synonymous variants: 163 observed, 148.64 expected, observed/expected ratio (o/e) 1.1, 90% interval 0.96 to 1.25.
Gene-disease validity (ClinGen):
ClinGen rates the evidence that SNAI1 causes each of these diseases.
congenital heart disease (autosomal dominant): Limited. A heart disease that is present at birth.
Homologues: Orthologues: chimpanzee SNAI1 (98% identical), macaque SNAI1 (98% identical), guinea pig SNAI1 (90% identical), pig SNAI1 (89% identical), mouse Snai1 (88% identical), dog SNAI1 (87% identical), rat Rnf114 (81% identical), rabbit SNAI1 (80% identical), tropical clawed frog snai1 (58% identical), zebrafish snai1a (51% identical), zebrafish snai1b (51% identical), Caenorhabditis elegans snai-1 (31% identical). Paralogues in human: SNAI2 (55% identical), SNAI3 (44% identical), SCRT2 (35% identical), SCRT1 (33% identical), ZNF410 (23% identical), PRDM1 (22% identical), HIC1 (21% identical), ZNF362 (21% identical), ZNF384 (21% identical), ZNF76 (21% identical), HIC2 (20% identical), ZBTB16 (20% identical), and 24 more.
Diseases named in the same sentence as SNAI1 in open-access papers:
SNAI1 is named in the same sentence as 260 diseases in open-access papers, as found by Europe PMC text mining. Sharing a sentence is not in itself a finding about the gene and the disease. The quoted sentences say what the papers report.
breast cancer (460 papers, 2005 to 2026). A primary or metastatic malignant neoplasm involving the breast. "In breast cancer, SNAI1 levels were also associated with both incidence of cancer relapse and poor patient survival." (PMID 40332096, 2025). "Analysis of established proteins of the epithelial and mesenchymal program of breast cancer cells clearly supports the notion that loss of SNAI1 enforces an epithelio-mesenchymal phenotype." (PMID 36171192, 2022). "In ZEB1/miR-200-driven NSCLC models as well as in SNAI1-driven breast cancer models, EMP was associated with PD-L1 expression." (PMID 35582229, 2020). "On the contrary, BAPTA-AM had opposite effects on two EMT transcription factors- it increased levels of TWIST1, but decreased the EGF- induced expression of SNAI1, a factor associated with decreased relapse-free survival in women with breast cancer." (PMID 30034631, 2018). "The expression of another EMT regulator i.e. SNAI1 has also been correlated with an increased risk of tumor relapse and poor survival in breast cancer patients, and with the progression of colorectal cancer." (PMID 24565133, 2014). "The transcription factor SNAI1 mediates epithelial-mesenchymal transition; thus, loss of SNAI1 may lead to lineage plasticity, which could explain some of the phenotypes in heterogeneous breast cancers." (PMID 39180549, 2024). "Loss of SNAI1 may lead to lineage plasticity that could explain some of the phenotypes in heterogeneous breast cancers." (PMID 36171192, 2022). "Moreover, the association between endogenous FBXL10 and SNAI1 was also confirmed in the breast cancer cells." (PMID 34718323, 2021). "Further, AHR hyper-activation with the endogenous ligand FICZ induced migration and invasion-associated (Snai1, Twist1, Twist2, Tgfb1, Vim) and stem cell-associated (Notch1, Notch2, Bmi1, Nanog, Sox2, Dppa3) genes in triple negative ALDHhigh breast cancer CSCs." (PMID 33396563, 2020). "However, it has been demonstrated that there is a link between reduction in breast cancer cell invasion caused by SNAI1-triggered epithelial to mesenchymal transition (EMT) and the down-regulation of Nectin-1." (PMID 24386110, 2013). "Inhibition of IL-6 signalling pathway through neutralising IL-6 antibody and siRNA found both breast cancer cell lines exhibited decreased migratory and invasive potential with reduced SNAI1 transcription." (PMID 40371393, 2025). "In tumors, the expression of SNAI1 and SNAI2 leads to decreased E-cadherin levels and enhanced tumor cell metastasis, and it is associated with the poor prognosis of breast cancer patients." (PMID 40830747, 2025). "In non-small-cell lung cancer (NSCLC) and in breast cancer, SNAI1 has been correlated with cancer aggressiveness." (PMID 40332096, 2025). "This role of SNAI1 as main TF-driving EMT has been further supported in breast cancer stem cells, where SNAI1 successfully regulated the transcription of EMT-related genes." (PMID 40332096, 2025). "Compressed breast cancer cells transfected with siRNA-IL-6 exhibited a sharp decrease in SNAI1 protein levels compared to cells transfected with siRNA-Control." (PMID 40371393, 2025). "As a result of IL-6 and SNAI1 upregulation, compressed breast cancer cells exhibit a more aggressive metastatic phenotype and are more likely to undergo migration and invasion to distal sites." (PMID 40371393, 2025). "For instance, KDM5B and SNAI1 activities exhibited gradually increased in ER+ cells, aligning with their known roles in breast cancer metastasis." (PMID 40397381, 2025). "SNAI1, also known as snail family transcriptional repressor 1 (SNAIL1), plays a crucial role in breast cancer progression and metastasis." (PMID 38890750, 2024). "The MMTV-PyMT transgenic mouse model develops mammary tumors with high incidence of Snai1-dependent spontaneous lung metastasis." (PMID 35883651, 2022).
breast cancer (continued). "O-GlcNAcylated MORC2 governs the expression of TGF-β1 target genes connective tissue growth factor (CTGF) and snail family transcriptional repressor 1 (SNAIL) and is crucial for breast cancer progression." (PMID 34974534, 2022). "Collectively, our data indicate that FOXA1 expression is essential in promoting cellular plasticity across the basal/luminal spectrum which is mainly dictated by the EMT-TF SNAI1 in breast cancer cells." (PMID 36171192, 2022). "F-box and leucine-rich repeat protein 10 (FBXL10) interacting with SNAI1 promoted the migration and invasion of breast cancer cells by inhibiting CDH1 expression and inducing EMT." (PMID 35464064, 2022). "The correlations between SNAI1 expression and the immune cells infiltration in breast cancer subtypes were also analyzed." (PMID 35898399, 2022). "Previous studies have shown overexpression of mesenchymal markers EGFR, CSV and SNAI1 after treatment with nab-paclitaxel in breast cancer cell lines." (PMID 35719960, 2022). "In breast cancer, SNAI1 controls the inhibition of fructose-1,6-bisphosphatase 1 (FBP1) in order to stimulate glycolysis." (PMID 35736645, 2022). "DDR2 expression was also independently correlated with FOXQ1 and SNAI1 across TCGA breast cancer data." (PMID 36713812, 2022). "Taken together, these results clearly suggest that STK39 enhances breast cancer metastasis, in large part, in SNAI1-dependent manner." (PMID 34335956, 2021). "Recent work highlights the role of USP37 in stimulating the epithelial-mesenchymal transition and metastasis in lung and breast cancer by stabilizing SNAI1 and stimulating the sonic hedgehog pathway, respectively." (PMID 34758854, 2021). "SNAI1 induces resistance to apoptosis, confers tumor recurrence and drug resistance, generates breast cancer stem cell (CSC)-like properties, and induces aerobic glycolysis." (PMID 34681726, 2021). "NCOA3 is amplified and expressed in a wide spectrum of human malignancy diseases, and studies have demonstrated that NCOA3 promoted EMT via the PI3K/AKT signalling in gastric cancer or through SNAI1 activation in breast cancer." (PMID 33289330, 2021). "In contrast to PEBP1’s role in metastasis, SNAI1 induced breast cancer EMT and metastasis by directly repressing the epithelial markers E-cadherin (CDH1)." (PMID 34885208, 2021). "Our studies clearly showed that STK39 controls EMT by stabilizing the CDH1 repressors of SNAI1 and is crucial for migration in breast cancer." (PMID 34335956, 2021). "SNAI1 induces resistance to apoptosis, confers tumor recurrence, generates breast cancer stem cell (CSC)-like properties, and induces aerobic glycolysis 14-16." (PMID 34335956, 2021). "The expression of CD44 in breast cancer cells can be upregulated through the activation of different EMT-related transcription factors including SNAI1 and SLUG." (PMID 33506060, 2021). "In the first study, the results highlighted that endogenous Snai1 expression was sufficient for breast cancer metastasis, also showing that Snai1 expression in breast cancer was transient and able to block MET process." (PMID 34768901, 2021). "The SRC-3-ERα complex directly bound to the ERα-binding site on the SNAI1 promoter, and increased the transcription of SNAI1, resulting in repression of E-cadherin expression in breast cancer." (PMID 33946224, 2021). "On the other hand, high ROS levels, along with metabolic alterations, contribute to the EMT process through the activation of the transcription factor SNAI1 in breast cancer cells." (PMID 33506060, 2021).
breast cancer (continued). "Upregulation of PPIL2 was reported to inhibit EMT and tumor invasion by interacting with the classical EMT transcription factor, SNAI1, to enhance its ubiquitin-dependent degradation in breast cancer." (PMID 34616428, 2021). "In contrast to the effects observed in breast cancer cells, CdGAP depletion in PC-3 cells led to a significant increase in SNAIL1 (SNAI1) and a decrease in E-cadherin (CDH1) mRNA and protein levels." (PMID 34493786, 2021). "SNAI1 is widely regarded as a master driver of epithelial-mesenchymal transition (EMT) and associated with breast cancer progression and metastasis." (PMID 34335956, 2021). "Martin and colleagues found SNAI1 to be overexpressed in invasive metastatic breast cancer compared to normal breast tissue." (PMID 34885208, 2021). "Inhibition of USP17 promotes SNAI1 degradation, thereby suppressing breast cancer invasion and metastasis." (PMID 33194625, 2020). "Before we correlate the expression of Snail1 and A20 in breast cancer cell lines, we performed Kaplan–Meier survival analysis to determine the probability of relapse-free survival when the expression of LASP1 and SNAI1 are high in human TNBC tumors." (PMID 32825729, 2020). "EMT is negatively controlled by miR-34 that targets EMT-triggering factors, such as zinc finger E-box binding homeobox 1 (ZEB1) and snail family transcriptional repressor 1 (SNAI1) in breast cancer." (PMID 33066509, 2020). "In contrast, MCF-7 cells overexpressing Nav1.5 display an increased invasive capacity, as well as an increased expression level of SNAI1, which provides evidence for the role of SNAI1 in Nav1.5 activity-mediated invasive process of breast cancer." (PMID 32792949, 2020). "We reported a similar finding in PBMCs from breast cancer patients, who have significantly lower SNAI1 expression compared with healthy controls." (PMID 31106153, 2019). "Previously, we showed that SNAI1 expression in the immune cells collected from the peripheral blood of breast cancer patients was significantly higher in patients with stage I disease compared with higher stages." (PMID 31106153, 2019). "First, we generated a score based on the average gene expression of PAPP-A/SNAI1/COL1A1 from a publicly available dataset of 327 patients with primary breast cancer (GSE20685)." (PMID 31046834, 2019). "miR-125b is reported to play tumor suppressive roles via targeting KIAA1522, ETS1, and SNAI1 in breast cancer." (PMID 31750242, 2019). "Snail expression in breast cancer metastasis was shown to be transient, whereas forced and prolonged expression of Snai1 decreased lung metastasis." (PMID 30258818, 2018). "We also tested the effect of 2APB on SNAI1 expression in the metastatic MDA-MB-231 breast cancer cell line." (PMID 30034631, 2018). "We provided a comprehensive model demonstrating that PPIL2 inhibits EMT and metastasis in breast cancer through cytoskeleton remodeling and by modifying SNAI1 ubiquitination." (PMID 29352246, 2018). "SNAI1 is also positively correlated with metastatic tumors, and high levels of SNAI1 are predictive of decreased relapse-free survival in women with breast cancer." (PMID 30034631, 2018). "A recent study showed that POU2F1 regulates expression of the EMT genes Twist1, Snai1 and Snai2 under hypoxia-dependent loss of PER2 in breast cancer." (PMID 28489585, 2017). "We found strong positive correlations between SIX1, SNAI1 or TWIST1 with GLI1 (a Hh pathway target) in numerous breast cancer data sets." (PMID 28604738, 2017). "Most available data are focused on breast cancer, where SNAI1/2 transcription factors induce AXL expression together with regulation of the expression of key EMT genes." (PMID 28251492, 2017). "In comparison, mammary tumor initiating cells with properties of CSCs are highly SNAI1 positive and display a stronger mesenchymal phenotype, including complete loss of E-cadherin expression, detachment, acquisition of motility, and lack of ZEB1 expression." (PMID 28758926, 2017).